NLRP3 (NLR family pyrin domain containing 3)
Diseases named in the same sentence as NLRP3 in open-access papers (continued):
Sharing a sentence is not in itself a finding about the gene and the disease.
peritonitis (continued). "BHB ameliorated caspase-1 activation and IL-1β release in NLRP3-dependent diseases such as familial cold autoinflammatory syndrome, Muckle-wells syndrome, and, urate crystal-mediated peritonitis." (PMID 38421496, 2024). "The LPS intraperitoneal injection-induced endotoxic shock and monosodium urate crystal (MSU)-induced peritonitis mouse models are widely used to assess NLRP3-dependent inflammasome responses in vivo." (PMID 38583156, 2024). "Carvedilol has antipyroptotic effects and can protect against peritonitis by inhibiting the activation of NLRP3 inflammasomes and macrophage pyroptosis." (PMID 39619569, 2024). "Altogether, these results demonstrate that Vitenegu acid inhibits NLRP3 inflammasome activation and subsequent immune cell recruitment accumulation in mouse peritonitis." (PMID 37153555, 2023). "The MSU-induced peritonitis model was used to investigate the inhibitory effects of Crocin on NLRP3-mediated inflammation." (PMID 36975504, 2023). "In this study, we investigated the inhibitory effect of Crocin on NLRP3 inflammasomes in mouse macrophages and a mouse peritonitis model." (PMID 36975504, 2023). "MSU crystals that act as an endogenous danger signal are known to induce gout disease or peritonitis by triggering NLRP3 inflammasome activation." (PMID 37047051, 2023). "The intraperitoneal injection of MSU leads to NLRP3 inflammasome-dependent peritonitis, which is characterized by IL-1β and IL-18 production and the neutrophil influx into the peritoneal cavity." (PMID 36975504, 2023). "We conclude that neutrophils orchestrate acute thioglycollate-induced peritonitis by producing IL-1β in an NLRP3-dependent manner." (PMID 36494392, 2022). "MSU crystal-induced peritonitis is another well-established NLRP3-dependent acute inflammatory model characterized by IL-1β secretion and massive neutrophil infiltration in peritoneal cavity." (PMID 35250572, 2022). "To verify above findings of PARP-1 in mediating NLRP3 activation in animals, we used the peritonitis model in WT and Parp-1−/− mice." (PMID 35098371, 2022). "We suggest that this reduced presence of P-selectin on the endothelial surface in Nlrp3-/- mice is responsible for the reduced recruitment of leukocytes, with a specific focus on neutrophils in the thioglycollate-induced peritonitis model." (PMID 36494392, 2022). "The protective role of BHB in NLRP3-driven diseases such as Muckle–Wells syndrome, urate crystal–induced peritonitis, and familial cold autoinflammatory syndrome has been validated in rodent models." (PMID 36741414, 2022). "Our study suggests an important role of Nlrp3 and neutrophils in promoting endothelial cell activation during acute inflammation observed in the mouse thioglycollate-induced peritonitis model." (PMID 36494392, 2022). "To evaluate the role of NLRP3 in neutrophils in endothelial activation, which is still elusive, we used the thioglycollate-induced peritonitis model characterized by an early neutrophil influx, on Nlrp3−/− and Nlrp3+/+ mice." (PMID 36494392, 2022). "Ori is preventative and therapeutic in mouse models of peritonitis, type 2 diabetes (T2D), and gouty arthritis, via blocking NLRP3 activation." (PMID 34566976, 2021). "Based on the findings of a previous study showing that an MSU-induced model of peritonitis is dependent on NLRP3 inflammasome activation, the levels of inflammatory indicators of peritonitis: peritoneal neutrophils and IL-1β were analyzed." (PMID 34512673, 2021). "In another MSU-induced peritonitis model, PL exhibited similar effects by suppressing IL-1β production and neutrophil infiltration, both of which were dependent on NLRP3 inflammasome." (PMID 35095532, 2021). "In another MSU-induced peritonitis model, PL also exhibited inhibitory effects on NLRP3 inflammasome reflected by reduced IL-1β and recruitment of neutrophils in the lavage fluid." (PMID 35095532, 2021).
peritonitis (continued). "A mouse model of MSU-induced peritonitis characterized by massive neutrophil influx and IL-1β production was established to define the suppressive effects of KM on the NLRP3 inflammasome in vivo." (PMID 33542692, 2020). "The inhibitory effects of 4-HAB on the NLRP3 inflammasome were further confirmed in a mouse model of MSU crystals-induced peritonitis." (PMID 31979265, 2020). "MSU-induced peritonitis is regarded as a typical animal model of NLRP3-IL-1β axis-dependent inflammation." (PMID 33542692, 2020). "VDR, an endogenous regulator of NLRP3, mitigates inflammasome-related inflammation in vivo, such as LPS-induced systemic inflammation and alum-induced peritoneal inflammation." (PMID 31866999, 2019). "In vivo, acetate protects mice from NLRP3 inflammasome-dependent peritonitis and LPS-induced endotoxemia." (PMID 31337751, 2019). "To evaluate the impact of HSP70 on NLRP3 inflammasome activation, we used in vivo crystal-induced peritonitis models." (PMID 30874540, 2019). "Neutrophil influx is impaired in an in vivo model of crystal-induced peritonitis in Nlrp3−/−, Asc−/−, Casp-1/Caspase-11−/−, and Il-1r−/− mice." (PMID 31803174, 2019). "To adapt MSU- and alum-induced peritoneal inflammation, which have been proven to be NLRP3 inflammasome-dependent models, and LPS-induced peritonitis, we pretreated mice with acetate intraperitoneally to investigate its anti-inflammatory effects." (PMID 31337751, 2019). "NRF2 is required for L-1β secretion and NLRP3 inflammasome activation, and the NLRP3 inflammasome can contribute to peritonitis in PD patients." (PMID 31156443, 2019). "Intraperitoneal injection of MSU elicited an NLRP3‐dependent peritonitis characterized by IL‐1β production and massive neutrophil influx." (PMID 29531021, 2018). "The mice also showed increased recruitment of neutrophils and monocytes to the peritoneum in alum-induced peritonitis through hyperactivation of the NLRP3 inflammasome." (PMID 29868015, 2018). "Collectively, these data indicated that BOT-4-one has a useful protective effect on MSU-induced peritonitis by inhibiting the NLRP3 inflammasome-mediated IL-1β production." (PMID 29118366, 2017). "We demonstrated that BOT-4-one exhibited a potent inhibition of the NLRP3 inflammasome in both mouse and human cells and in a peritonitis mouse model." (PMID 29118366, 2017). "This agrees with our results showing that blockade of NLRP3 inflammasome with glybenclamide in the ITO-NP–mediated peritonitis mouse model principally reduced the influx of neutrophils and IL-1β production." (PMID 27194621, 2016). "In vivo experiments also confirmed the beneficial roles of TRIM31 in the alum-induced peritonitis, an NLRP3 dependent acute inflammatory model." (PMID 27929086, 2016). "Here, mice intraperitoneally inoculated with ITO-nanoparticles (ITO-NPs) resulted in peritonitis dependent in NLRP3 inflammasome, with neutrophils recruitment and interleukin-1β (IL-1β) production." (PMID 27194621, 2016). "Peritonitis induced by ITO-NPs was diminished by impeding NLRP3 inflammasome activation by a sulfonylurea pharmacological inhibitor, glybenclamide (Gly)." (PMID 27194621, 2016). "In vivo, we showed that genipin inhibited NLRP3-dependent IL-1β production and neutrophil flux in LPS- and alum-induced murine peritonitis." (PMID 26659006, 2015). "We found that inhibition of the NLRP3 inflammasome attenuated myocardial dysfunction in mice with LPS and increased the survival rate in mice with feces-induced peritonitis." (PMID 25216263, 2014). "We also assessed SENP6’s role in NLRP3-driven peritonitis via intraperitoneal alum injection." (PMID 41531891, 2026). "Furthermore, the protective effect of DCL against MSU‐induced peritonitis mediated by NLRP3 inflammasome activation was investigated." (PMID 40919130, 2025).
peritonitis (continued). "The MSU-induced peritonitis model was used to investigate the regulatory role of USP13 in the activation of the NLRP3 inflammasome in vivo, which is a well-established NLRP3-dependent acute inflammatory model characterized by IL-1β secretion and massive neutrophil influx into the peritoneal cavity." (PMID 41004574, 2025). "To further test the effect of BI6727 in vivo, we also used an MSU-induced peritonitis model, in which IL-1β levels were completely dependent on NLRP3 activation and the increased IL-1β levels upon MSU treatment led to neutrophil infiltration into the peritoneal cavity." (PMID 37698938, 2023). "To assess whether overexpression of Nlrp3 in the MK lineage plays a role in the setting of inflammation, we used peritonitis induced by intraperitoneal injection of zymosan." (PMID 37622117, 2023). "Finally, in Kunming mice with peritonitis, NLRP3 and IL-1β expression in the peritoneum were evaluated." (PMID 36077562, 2022). "In addition, Nlrp3+/+ neutrophils, infiltrated in the peritoneal cavity at early stages (1 h) after thioglycollate induced peritonitis, showed inflammasome assembly as ASC speck formation." (PMID 36494392, 2022). "In addition, the study showed that acetate had a protective effect on NLRP3‐dependent peritonitis in vivo." (PMID 33682108, 2021). "In NLRP3 dependent peritonitis models, effector T cells reduced neutrophils recruitment in an antigen-dependent manner, demonstrating that T cells inhibit innate immune response by inhibiting NLRP3 inflammasomes." (PMID 34381452, 2021). "Finally, we determined the in vivo role of AIM in the inhibitory effects of IL-10 on inflammatory responses and NLRP3 inflammasome activation in lipopolysaccharide (LPS)-induced acute peritonitis using wild type (WT) and AIM−/− mice." (PMID 33414479, 2021). "Moreover, PL alleviated the lipopolysaccharide (LPS)-induced endotoxemia and MSU-induced peritonitis in vivo, which are NLRP3-dependent inflammations." (PMID 35095532, 2021). "Recently, the NOD-like receptor family, pyrin domain-containing 3 (NLRP3) inflammasome was found to be activated in the peritoneal tissues of acute bacterial peritonitis in patients on PD, and blockade of NLRP3 rescued morphologic alterations during acute peritonitis." (PMID 34084773, 2021). "Furthermore, PL suppressed lipopolysaccharide-induced endotoxemia and MSU-induced peritonitis in vivo, which are NLRP3-dependent inflammation." (PMID 35095532, 2021). "Moreover, treatment with GSK2837808A reduced MSU-mediated peritonitis in mice, a disease model used for studying the consequences of NLRP3 inflammasome activation." (PMID 33854503, 2021). "Our results indicate that AIM might be specifically targeted as an inhibitor of NLRP3 inflammasome activation for therapeutic intervention of several inflammatory diseases, including peritonitis." (PMID 33414479, 2021). "Despite the acetate have shown anti-inflammatory effects by regulating NLRP3 in several peritonitis models, its role in BPD remains unknown." (PMID 33614540, 2020). "In addition, acetate reduces the activation of NLRP3 through ubiquitination and autophagy and plays an anti-inflammatory role in peritonitis and endotoxemia models." (PMID 33614540, 2020). "To test whether the NBC molecules could inhibit NLRP3-dependent inflammation in vivo, we used a previously reported model of peritonitis." (PMID 28943355, 2017). "Moreover, the clinical-trial-tested Pyk2/FAK dual inhibitor PF-562271 reduced monosodium urate-mediated peritonitis, a disease model used for studying the consequences of NLRP3 activation." (PMID 27796369, 2016). "Studies have shown that the activation of the endothelial NLRP3 inflammasome contributes to peritoneal inflammation and fibrosis in patients with CKD on PD and is also associated with defects in solute transport and tissue remodeling during PD-related peritonitis." (PMID 40725180, 2025).
peritonitis (continued). "The aberrant activation of NLR family, pyrin domain-containing 3 (NLRP3) inflammasomes—a protein complex assembled of NLRP3, apoptosis-associated speck-like protein (ASC), and cysteinyl aspartate specific proteinase (casp-1)—contributes to the development of peritonitis." (PMID 36077562, 2022). "This study aimed to explore the inhibitory effect of KM on NLRP3 inflammasome activation and the underlying mechanisms both in vitro using macrophages stimulated with LPS plus ATP, nigericin or monosodium urate (MSU) crystals and in vivo using an MSU-induced peritonitis model." (PMID 33542692, 2020). "Finally, BOT-4-one appeared to be superior to other known NLRP3 alkylators in inhibiting the functionality of the NLRP3 inflammasome and its resulting anti-inflammatory activity was confirmed in vivo using a monosodium urate-induced peritonitis mouse model." (PMID 29118366, 2017). "focused on in vitro models, our study utilized in vivo models of ALI and peritonitis, offering a more complex, physiologically relevant context for observing SENP6’s role in NLRP3 regulation." (PMID 41531891, 2026). "We established a model of peritonitis in mice by intraperitoneal (i.p.)injection of MSU, in which inflammation is NLRP3 inflammasome dependent." (PMID 39218978, 2024). "In mouse models, LicoB exhibited protective role in LPS-induced septic shock, MSU-induced peritonitis, and non-alcoholic steatohepatitis (NASH) via hindering the activation of NLRP3." (PMID 38421496, 2024). "In this study, we demonstrate that Crocin suppresses the signal 2 process of the NLRP3 inflammasome by inhibiting mtROS production and alleviates monosodium urate (MSU)-induced peritonitis." (PMID 36975504, 2023). "Our data revealed that 149-01 effectively alleviate LPS-induced systemic inflammation, MSU-induced peritonitis and EAE at a dose of 5 mg/kg and its therapeutic effect is dependent on NLRP3." (PMID 35250572, 2022). "To confirm the role of YAP in regulating NLRP3 inflammasome activation in vivo, we injected i.p. the mice with monosodium urate (MSU), which induces neutrophil infiltration and peritonitis in a NLRP3 dependent manner." (PMID 33976226, 2021). "In the absence of the Trx1 system, we observed drastically impaired IL-1β production in response to classical NLRP3 stimuli in vitro and during MSU-induced peritonitis in vivo, while pro-Il1b transcription was unaltered." (PMID 32096759, 2020). "We screen CLANs both in vitro and in vivo and select a preferable CLAN to deliver mCas9/gNLRP3 into macrophages, which ameliorates LPS-induced septic shock, MSU-induced peritonitis and HFD-induced T2D by disrupting NLRP3 in macrophages." (PMID 30291237, 2018). "To better determine the contribution of POH1 to the regulation of NLRP3-induced inflammation, we investigated the function of POH1 in the alum-induced, NLRP3 inflammasome-dependent peritonitis mouse model." (PMID 30315153, 2018). "Based on the potent inhibition of NLRP3 inflammasome activation, we assessed the utility of BOT-4-one as an anti-inflammatory agent by using a peritonitis mouse model." (PMID 29118366, 2017). "Given that SHP2 inhibits NLRP3 inflammasome activation in vitro, we further examined the role of SHP2 in the alum-induced murine peritonitis model." (PMID 29255148, 2017). "In a mouse model, we found that PF-562271 can inhibit NLRP3-mediated IL-1β secretion and reduce MSU-induced peritonitis." (PMID 27796369, 2016). "Given that LRRFIP2 inhibits NLRP3 inflammasome activation in vitro, we further demonstrated the biological effect of LRRFIP2 in vivo by knocking down LRRFIP2 in a mouse peritonitis model." (PMID 23942110, 2013). "In this study, we investigated the effects of Crocin on the activation of the nucleotide-binding oligomerization domain, leucine-rich repeat, and pyrin domain containing 3 (NLRP3) inflammasome in J774A.1 murine macrophage cells and monosodium urate (MSU)-induced peritonitis." (PMID 36975504, 2023).
peritonitis (continued). "Although we have not assayed changes in IL-18 during peritonitis, our analysis of IL-1β production suggests the rapid activation of the NLRP3 inflammasome system following SES challenge." (PMID 37272871, 2023). "Moreover, 149-01 treatment effectively attenuated several NLRP3-related inflammatory diseases in mice, including LPS-induced systemic inflammation, MSU-induced peritonitis and EAE." (PMID 35250572, 2022). "In air pouch inflammation and peritonitis mouse models, POVPC injection resulted in the production of caspase-1 (p10), IL-1β, and IL-18 in wild-type mice but not in NLRP3-deficient mice." (PMID 33534121, 2021). "In a mouse model of MSU-induced peritonitis, macrophages from mice lacking the key components of NLRP3 inflammasome, e.g., NLRP3, caspase-1, or ASC, were incapable of producing the active form of IL-1β in response to MSU challenge." (PMID 33785039, 2021). "We next addressed the negative role of VDR in NLRP3 inflammasome activation using an alum-induced peritonitis model." (PMID 31866999, 2019). "Previous reports have shown that the inhibition of the NLRP3 inflammasome by EGCG may lead to the suppression of lupus nephritis and peritonitis in mouse models." (PMID 31174271, 2019). "Dopamine-mediated DRD1 signaling also prevents both LPS-induced systemic inflammation and MSU-induced peritonitis through suppression of IL-1β production via inhibition of NLRP3 inflammasome activation, but not by suppression of TNF-α." (PMID 29868015, 2018). "CLANmCas9/gNLRP3 was unable to entirely prevent septic shock and peritonitis likely because of the activation of other inflammasomes, such as NLRP1, NLRC4, and AIM23,5,7, and the inactivation of the NLRP3 inflammasome was insufficient to inhibit acute inflammation." (PMID 30291237, 2018). "More importantly, the previous study focused on an alum-induced peritonitis model, and found that TRIM31 could inhibit NLRP3 inflammasome activity in mouse peritonitis in vivo." (PMID 29497383, 2018). "From the study, it is evident that the absence of HSP70 exacerbates NLRP3-dependent peritonitis and enhances caspase-1 activation and IL-1β production in bone marrow-derived macrophages (BMDMs) of mice, while also increasing the number and size of ASC/NLRP3 specks." (PMID 40297581, 2025).